VDR (vitamin D receptor)
Diseases named in the same sentence as VDR in open-access papers (continued):
Sharing a sentence is not in itself a finding about the gene and the disease.
oral cancer (continued). "The results of this detailed investigation illuminate the complex interaction between variations in the VDR gene and the development of tobacco-related oral cancer." (PMID 40356850, 2025). "Several studies that focused on genetic polymorphisms and the expression of the 1,25 dihydroxyvitamin D3 receptor (VDR) suggested significant associations with vitamin D and increased oral cancer risk and worse survival rates." (PMID 37242229, 2023). "Another study has revealed that VDR expression was increased in premalignant lesions and oral cancer, and vitamin D supplementation significantly diminished therapy-related toxicities in late-stage oral cancers, with less morbidity and better quality of life." (PMID 32438644, 2020). "Lastly, Vitamin D can prevent apoptosis resistance in oral cancer cells by modulating the VDR expression in precancerous lesions." (PMID 31216637, 2019). "Key words:Oral cancer, oral precancer, lichen planus, leukoplakia, apoptosis, serum 25(OH)D3, vitamin D receptor, chemoprevention, multistep carcinogenesis." (PMID 25662556, 2015). "The investigation included three primary components: the VDR gene, oral cancer, and tobacco." (PMID 40356850, 2025). "The vitamin D receptor (VDR) plays a critical role in the pathogenesis of oral cancer." (PMID 38476562, 2024). "Vitamin D (VitD) and its receptor (VDR) have been extensively studied for their potential contributions to the prevention and therapeutic management of various diseases and neoplastic conditions, including oral cancer." (PMID 37894739, 2023). "Moreover, excessive alcohol consumption has been associated with VDR CYP27B1 polymorphism, which is correlated with an increased risk for oral cancer." (PMID 37242229, 2023).
renal fibrosis (14 papers, 2016 to 2025). A final common manifestation of a wide variety of chronic kidney diseases characterized by glomerulosclerosis and tubulointerstitial fibrosis. "The loss of VDR can lead to renal fibrosis by affecting perirenal inflammation and epithelial-mesenchymal transition (EMT)." (PMID 31218132, 2019). "A mouse model of unilateral ureteral obstruction also demonstrated that the downregulation of VDR expression in renal tissue was associated with an epithelial mesenchymal transition and renal fibrosis." (PMID 29854030, 2018). "Multiple lines of evidence have shown that vitamin D and analogues decrease renal fibrosis progression via the vitamin D receptor and inhibit TGF-β1/Smad3 signaling pathway." (PMID 39787157, 2025). "An earlier report showed that active vitamin D3 inhibited renal fibrosis through promoting direct interaction VDR and Smad3." (PMID 31775746, 2019). "The beneficial effects of vitamin D on renal fibrosis in DN are mediated by VDR via restoration of α-klotho expression." (PMID 30250850, 2018). "Of note, this set of data indicated a closely connection between VDR expression and the complex process of renal fibrosis formation." (PMID 30370270, 2018). "A previous study showed that vitamin D supplementation suppresses renal fibrosis through stimulation of vitamin D receptor-mediated transcription, which inhibits TGF-β1-Smad signal transduction." (PMID 28779150, 2017). "The results showed that VDR protected against renal fibrosis in STZ mice." (PMID 38697845, 2024). "In this study, we showed that VDR could ameliorate renal fibrosis in STZ-induced diabetic mice by up-regulating the expression of BNIP3 and PINK1." (PMID 38697845, 2024). "Once sufficient, vitamin D could help to restore VDR and retard renal fibrosis formation by blocking EMT." (PMID 30370270, 2018). "Such a loss of VDR could render tubular epithelial cells susceptible to EMT and renal fibrosis induced by TGF-β and depression of β-catenin signaling." (PMID 30370270, 2018). "Besides, increasing VDR levels may alleviate proteinuria, renal fibrosis and inflammation and prevent podocyte damage." (PMID 38318147, 2024). "The results of our animal experiments suggested that both Tan and Par could protect DN rats by improving FBG, UACR, and BUN/SCr, reducing renal fibrosis, and inhibiting EMT by regulating VDR/Wnt/β-catenin pathway." (PMID 37991543, 2024). "Moreover, the administration of vitamin D to mice on the fifth day after the establishment of ureteral obstruction model could restore the expression of VDR and inhibit inflammatory reaction, thereby significantly reducing EMT and improving renal fibrosis." (PMID 37991543, 2024). "In other words, a non-classical VDR pathway suppresses renal fibrosis." (PMID 29270765, 2018).
thyroid cancer (14 papers, 2015 to 2025). "Another target in the vitamin D pathway implicated in thyroid cancer progression is the vitamin D receptor." (PMID 34298730, 2021). "The VDR polymorphism has association with variety of thyroid cancer and the benign thyroid nodules." (PMID 40008182, 2025). "There is evidence that VDR polymorphisms may be associated with the risk and aggressive forms of thyroid cancer." (PMID 38132395, 2023). "However, only two studies have investigated the association between VDR polymorphisms and thyroid cancer risk." (PMID 28895880, 2017). "The function of VDR in more aggressive forms of thyroid cancer, such as ATC, is less clear and needs to be explored further." (PMID 40071065, 2025). "Previous studies have shown that VDR expression decreases with tumor dedifferentiation in esophageal adenocarcinoma and increased malignant degree in thyroid carcinoma." (PMID 38639057, 2024). "To determine the expression of VDR in thyroid carcinoma, firstly, we used the UALCAN platform to explore the mRNA expression of VDR in THCA based on tumor histology." (PMID 38639057, 2024). "We also showed a differential expression of VDR (unpublished data) in thyroid cancer tissues; therefore, our lab is also focusing on VDR-Enigma interactions." (PMID 38132395, 2023). "Consistently, a higher protein level of VDR was observed in highly differentiated thyroid cancer cell lines (K1 cell)." (PMID 35099410, 2022). "Some associations between thyroid cancer risk (VDR, CYP24A1, DHCR7) or the clinical course of the disease (VDR) and vitamin D-related gene polymorphisms were described in the literature." (PMID 36362448, 2022). "Thus, the levels of VDR expression in malignant tissue of thyroid cancer are inversely associated with aggressive tumor characteristics, while increased expression of VDR in DTC might be one of the compensatory mechanisms for maintaining a relatively lower progression of the tumor." (PMID 35099410, 2022). "The upregulated expression of VDR in differentiation thyroid cancer was verified by gene expression analysis." (PMID 35099410, 2022). "A study evaluating the expression of VDR in thyroid cancer cells of different lines showed that VDR expression is at a different level, and a high level does not always provide a positive response to vitamin D therapy." (PMID 32197412, 2020). "Further investigations should be envisaged to address the functional role of RXRG, VDR, and the thyroid hormone receptor in thyroid cancer, especially in FVPTCs." (PMID 25923053, 2015). "Although there are variable levels of VDR expression, evidence suggests that VDR agonists may be of therapeutic benefit, especially in more differentiated thyroid cancer types such as papillary thyroid cancer." (PMID 40071065, 2025). "The interaction of the Enigma and VDR is important as we have found that advanced thyroid cancer has low expression levels of vitamin D binding protein (DBP) in advanced thyroid cancer tissues with a stage-dependent higher expression of the Enigma protein in the corresponding thyroid cancer tissues." (PMID 38132395, 2023). "A meta-analysis of the five studies of common VDR polymorphisms did not confirm their association with increased susceptibility to differentiated thyroid cancer." (PMID 36362448, 2022). "A total of seven studies assessing VDR SNPs in thyroid cancer were found." (PMID 36362448, 2022). "Therefore, the association between VDR to ECM1 and TMPRSS4, suggested a potential role of VDR in thyroid carcinoma." (PMID 28092021, 2017). "To further investigate the role of VDR in thyroid cancer tumorigenesis, we examined cell proliferation and differentiation of DTC cells in which VDR was underexpressed or overexpressed." (PMID 35099410, 2022). "Molecular studies have established clear connections between several targets in the vitamin D metabolism pathway and thyroid cancer, including CYP24A1 and VDR." (PMID 34298730, 2021).
thyroid cancer (continued). "It was characterized by the increased levels of VDR, CYP24A1 and CYP27B1 in benign and differentiated malignant thyroid tumors." (PMID 25501638, 2015). "Taken together, VDR inhibits DTC cell proliferation and promotes differentiation via regulation of the E-cadherin/β-catenin complex, potentially representing novel clues for a therapeutic strategy to attenuate thyroid cancer progression." (PMID 35099410, 2022).
vitiligo (14 papers, 2010 to 2025). Generalized well circumscribed patches of leukoderma that are generally distributed over symmetric body locations and is due to autoimmune destruction of melanocytes. "In 2014, a significant association between VDR gene polymorphisms and vitiligo susceptibility was reported, with the ApaI a allele and BsmI bb genotype linked to increased risk in East Asian populations." (PMID 41157208, 2025). "The interplay between VDR polymorphisms, serum 25(OH)D levels, and vitiligo has become a subject of clinical and epidemiological investigation." (PMID 41157208, 2025). "The association between VDR gene polymorphisms and serum 25(OH)-vitamin D3 levels has been studied in various pathological conditions, such as vitiligo, lumbar disc degeneration, and autism." (PMID 39519264, 2024). "A recent population-based study evaluated the relationship between genetic polymorphisms of the nuclear vitamin D receptor (VDR) gene and vitiligo patients’ response to narrowband UVB phototherapy in a sample of Egyptians22." (PMID 36854764, 2023). "Several VDR gene polymorphisms were studied in vitiligo such as ApaI (VDR 7975232 C > T), BsmI (VDR1544410 A > G), FokI (VDR 2228570 C > T), and TaqI (VDR 731236 T > C)." (PMID 35318513, 2023). "Further investigations for the role of different types of VDR gene polymorphisms in different types of vitiligo and in response to phototherapy are strongly recommended with larger sample size and longer durations of treatment and follow-up." (PMID 35318513, 2023). "They found that the dominant genetic model (aa + Aa vs. AA), recessive genetic model (aa vs. Aa + AA), and allelic contrast model (a vs. A) of ApaI in the VDR gene were associated with a significant increased risk of vitiligo." (PMID 35318513, 2023). "Zhang JZ evaluated possible associations between ApaI, BsmI, TaqI, and FokI VDR SNPs, serum 25 (OH)D, and the risk of vitiligo by analyzing 17 articles." (PMID 37508347, 2023). "Various factors have been implicated in the etiopathogenesis of vitiligo including the role of calcium imbalance, vitamin-D receptor-Apa-1 polymorphism, and low levels of circulating 25-OH vitamin D." (PMID 25006488, 2014). "VDR gene encoding vitamin D receptor in 12q13 locus associates with vitiligo in a small inbred Romanian community." (PMID 20377893, 2010). "Genetic abnormalities in major histocompatibility complex (MHC) class I and III along with vitamin D receptor polymorphisms may be the predisposition to the development of both AD and vitiligo." (PMID 36614274, 2023). "Moreover, many studies about the association between VDR gene polymorphisms and susceptibility to vitiligo provide interesting results." (PMID 36902117, 2023). "VDR gene polymorphisms may share in vitiligo pathogenesis and in vitiligo response to phototherapy as they may lead to VDR dysfunction and decreased vitamin D activity." (PMID 35318513, 2023). "Zhan’s meta-analysis revealed that VDR Apal polymorphism increased the susceptibility risk of vitiligo, and there is a positive correlation between serum vitamin D deficiency and the incidence of vitiligo." (PMID 32635380, 2020). "The role of vitamin D and its receptor polymorphisms in the pathogenesis of vitiligo has gained growing interest in recent years, with accumulating evidence suggesting that variations in the VDR gene may influence serum vitamin D levels and contribute to a genetic predisposition to vitiligo." (PMID 41157208, 2025). "VDR gene polymorphism (ApaI) may share in vitiligo pathogenesis and response to NB-UVB." (PMID 35318513, 2023). "In another study, cutaneous VDR expression and serum 25(OH) vitamin D level in vitiligo patients were significantly lower compared to controls." (PMID 35318513, 2023). "It was observed that in patients affected by vitiligo, VDR expression was remarkably reduced in the areas of “lesional/perilesional” skin, while re-pigmentation was accompanied by an increase in VDR expression." (PMID 36902117, 2023).
vitiligo (continued). "The current work aimed at evaluating the possible association between VDR gene polymorphisms (TaqI and ApaI) and susceptibility of vitiligo and if they could be predictors of response to NB-UVB phototherapy in Egyptian vitiligo patients." (PMID 35318513, 2023). "Additionally, in this pathology, vitamin D and its action on the vitamin D receptor (VDR) create the basis for a connection between vitiligo and OP." (PMID 32635380, 2020).
renal cell carcinoma (13 papers, 2009 to 2024). "Asian populations are more susceptible to renal cell cancer (RCC) due to the VDR gene polymorphisms Apa1 and Fok1 (FF genotype)." (PMID 39335182, 2024). "We designed a case-control study to investigate the effect of vitamin D receptor gene (VDR) gene single nucleotide polymorphisms (SNPs) and possible gene- environment interaction on the susceptibility of renal cell carcinoma (RCC)." (PMID 34006324, 2021). "This study aimed to investigate the genetic association of VDR polymorphisms with renal cell carcinoma (RCC) risk in the Chinese population." (PMID 27174575, 2016). "However, few reports are available on association between VDR polymorphism and renal cell carcinoma and the obtained results are inconsistent." (PMID 25945350, 2015). "ApoE-/- upregulated IL-6, Renal cell carcinoma, PRRs in recognition of bacteria and viruses, VDR/RXR activation, Phenylalanine degradation IV pathways in Ly6Chigh MC." (PMID 34987524, 2021). "However, up to now, there is no study on the relationship between VDR gene and environmental factors and the risk of renal cell carcinoma." (PMID 34006324, 2021). "Therefore, analysis of genetic variation in VDR and other vitamin D pathway genes may provide insight into the role of vitamin D in renal cell carcinoma (RCC) etiology." (PMID 19753122, 2009). "However, the concert of genes that interact with VDR is vast; therefore, an analysis of variation in VDR and other genes in the vitamin D pathway may provide insight into the role of vitamin D in renal cell carcinoma (RCC) etiology." (PMID 19753122, 2009).
uremia (13 papers, 2005 to 2025). A clinical syndrome associated with the retention of renal waste products or uremic toxins in the blood. "The induction of the VDR that occurs in the calvaria of the uremic rats differs from the major loss of VDR in other regulators of mineral metabolism as the parathyroid glands or the kidney during uremia." (PMID 25166750, 2014). "Since advanced uremia is a condition of 1,25-dihydroxyvitamin D deficiency, but also a deficiency and dysfunction of the vitamin D receptor, uremic effects associated with the vitamin D receptor may be involved in the SOD-2 changes." (PMID 32823917, 2020). "Since advanced uremia is a state of 1,25-dihydroxyvitamin D deficiency but also of vitamin D receptor deficiency and dysfunction, vitamin D receptor-related uremic effects could be involved in the J-shape of SOD2 protein that we observed." (PMID 27630759, 2016). "With late stage CKD (eGFR < 15 mL/min/1.73 m2), uremia can cause progressive loss of tissue VDR (clearly demonstrated in the parathyroids of uremic patients) and diminishing binding capacity between 1,25(OH)2D and VDR, leading to tissue vitamin D resistance." (PMID 27187460, 2016). "We launched the present study to examine whether the low expression of parathyroid CaR and VDR in uremia was associated with changes in methylation levels in vivo or in vitro." (PMID 23094155, 2012). "Parathyroid hormone (PTH) is normalized despite low levels of CaR and VDR after experimental reversal of uremia." (PMID 23094155, 2012). "Interestingly, parathyroid hormone secretion decreased significantly after reversal of uremia by homogeneic renal transplantation, while the expression of CaSR and VDR genes in parathyroid glands remained decreased." (PMID 36267284, 2022). "In this study, we employed paricalcitol to investigate whether VDR activation mitigates the detrimental effect of uremia on endothelial function in the 5/6 NX rats." (PMID 20169119, 2010). "The potential anti-inflammatory and immunomodulatory effects of 1,25(OH)2D3 via VDR and STAT5 crosstalk were also evaluated in human monocytes incubated with sera from DM2 patients and DN patients with uremia." (PMID 35054991, 2022). "After pretreatment with 1,25(OH)2D3, monocytic VDR mRNA and protein expression on nuclei and cell membrane was significantly up-regulated in T2DM and DN uremia groups." (PMID 35054991, 2022). "The present study found no signs of methylation in the parathyroids of uremic or normal rats, indicating that changes in methylation levels are not involved in the low expression of parathyroid CaR or VDR genes in uremia, either in vivo or in vitro." (PMID 23094155, 2012).
Arthritis (12 papers, 2014 to 2022). Inflammation of a joint. "Another genomic study focused on the VDR gene, which encodes the nuclear receptor VDR and is associated with 70% of the genetic effects on bone mass density and arthritis." (PMID 35739987, 2022). "The relevance of vitamin D in the pathogenesis of RA is supported by the observation that VDR-deficient mice are prone to a more severe arthritis when crossed with human TNF transgenic mice (hTNFtg), in comparison to VDR wild type/hTNFtg mice." (PMID 32192175, 2020). "A strong association with arthritis and Vitamin D Receptor (VDR) polymorphism was identified in the study conducted by de Azevêdo Silva and colleagues in 2013." (PMID 26798662, 2015). "In murine models 1,25(OH)2D was able to prevent the onset and progression of arthritis and VDR deficient mice (VDR−/−) showed a more aggressive disease." (PMID 25887374, 2015). "Similarly, the vitamin D receptor (VDR), which plays an important role in facilitating PBMC responses to 1,25(OH)2D in immune homeostasis, is altered in RA and VDR polymorphisms are linked to the development of arthritis." (PMID 32728658, 2020). "However, the current study was conducted to determine the vitamin D level in RA as well OA patients and to determine the susceptibility of VDR gene polymorphism with the onset of arthritis." (PMID 31011579, 2019). "A very detailed and comprehensive analysis regarding immunological processes, cytokines involved in bone resorption and bone turnover was performed in vitamin D receptor (VDR) knockout mice with spontaneously developing arthritis." (PMID 25315028, 2014). "A murine model of chronic arthritis, in which mice lacking VDR were interbred with human tumor necrosis factor (TNF) transgenic mice, showed that the absence of VDR exacerbated inflammation and the severity of arthritis." (PMID 35276806, 2022).